CCNL1 (cyclin L1)
Diseases named in the same sentence as CCNL1 in open-access papers:
CCNL1 is named in the same sentence as 39 diseases in open-access papers, as found by Europe PMC text mining. Sharing a sentence is not in itself a finding about the gene and the disease. The quoted sentences say what the papers report.
prostate carcinoma (9 papers, 2015 to 2025). A carcinoma that arises from epithelial cells of the prostate gland. "It has been reported that CCNL1 is associated with the development of various tumors, such as HNSCC, Ewin’s sarcoma, and prostate cancer." (PMID 39024509, 2024). "Previous reports have shown that CCNL1 is involved in regulating the occurrence and development of various tumors, such as head and neck cell carcinoma, prostate cancer, pancreatic cancer, EBV-positive nasopharyngeal carcinoma and uterine cervical carcinoma." (PMID 39024509, 2024). "As RUNX2 is a widely known vital marker and driver in bone metastatic prostate cancer, this CCNL1/CDK19/NEAT1-1 complex can significantly induce the bone metastasis of prostate cancer." (PMID 37069649, 2023). "These represented cell cycle/mitosis; among others CCNE1, CCNE2, CCNG2, CCNL1, CCNT1, CDK12 and CDKN3, prostate cancer; including the androgen receptor (AR), metabolism as well as targets of the transcription factors E2F, AP2, SP1, ETF and Pax3." (PMID 26698305, 2015).
head and neck squamous cell carcinoma (6 papers, 2005 to 2025). A squamous cell carcinoma that arises from any of the following anatomic sites: lip and oral cavity, nasal cavity, paranasal sinuses, pharynx, larynx, and salivary glands. "CCNL1, a cell cycle regulatory protein and a potential oncogene, is localized in the 3q25 region and associated with the survival rate of patients with head and neck squamous cell carcinoma." (PMID 26043836, 2015). "With regard to cancer, CCNL1 has been reported to be overexpressed in head and neck squamous cell carcinomas and thus is considered as a candidate proto-oncogene." (PMID 31357971, 2019). "For instance, CCNL1 was expressed and amplified in human head and neck squamous cell carcinoma, and was suggested as an oncogene." (PMID 26043836, 2015). "Transcriptional analysis in 20 head and neck squamous cell carcinomas showed the overexpression of CCNL1 in all the tissues." (PMID 17938736, 2007). "We evaluated the expression and amplification of cyclin L1 (CCNL1) gene, a potential oncogene localised in the commonly amplified 3q25–28 region, in human head and neck squamous cell carcinomas (HNSCCs)." (PMID 16598186, 2006).
Obesity (5 papers, 2016 to 2024). Accumulation of substantial excess body fat. "Co-localization analysis revealed mQTLs for cg21178254 methylation site upstream of CCNL1 gene co-localize with obesity risk SNPs (PSMR = 7 × 10−10, PHEIDI = 0.5)." (PMID 34207686, 2021). "Low-level methylation of the cg21178254 locus upstream of cyclin L1 (CCNL1) increased the expression of this gene and promoted obesity." (PMID 36397166, 2022). "By integrating expression quantitative trait locus (eQTL) data, we noted that lower methylation at cg21178254 site upstream of CCNL1 contributes to obesity by increasing the expression of this gene." (PMID 34207686, 2021). "We found that lower methylation at the cg21178254 site upstream of CCNL1 contributes to obesity by increasing the expression of this gene." (PMID 34207686, 2021). "As such, it appears methylation at this site contributes to obesity by changing the expression of CCNL1." (PMID 34207686, 2021). "These SNPs were in/near the following genes: LEP, SLC32A1 (solute carrier family 32 member 1), GCKR (glucokinase regulatory protein), CCNL1 (cyclin-L1), and FTO (fat mass and obesity-associated)." (PMID 31766143, 2019). "We took forward the genome-wide significant leptin loci near LEP, nearSLC32A1, in GCKR and near CCNL1, to examine theirassociations with obesity-related and metabolic traits and to more directlyassess their putative roles in the control of circulating leptin." (PMID 26833098, 2016).
breast carcinoma (4 papers, 2012 to 2024). "RNA expression levels of CDC2L1, CDC2L2, CCNL1, CCNL2, CSNK2A1, CSNK2A2, and CSNK2B genes in breast cancer subtypes were analyzed." (PMID 25837326, 2015). "We identified downregulated CARs in vicinity or overlapping the oncogenes IGF1R, MYLK, the breast cancer drug target OGT (O-GlcNAc transferase), and the breast cancer-related cyclin CCNL1." (PMID 25264628, 2014).
type 2 diabetes (4 papers, 2011 to 2021). "Recently, two birth weight-lowering loci on chromosome 3 (near CCNL1 and ADCY5) were identified in a genome-wide association study, the latter of which is also a type 2 diabetes locus." (PMID 21712988, 2011). "Previous genome-wide association studies of birth weight identified a variant in the ADCY5 (rs9883204) associated with birth weight and type 2 diabetes, and another variant, near CCNL1 (rs900400), associated with no obvious link to adult traits." (PMID 34267728, 2021). "However the CCNL1/LEKR has not yet been linked to either with type 2 diabetes or adult glycemic traits." (PMID 22685556, 2012).
diabetes (2 papers, 2019 to 2020). "Differential methylation between cases and controls was significant in both the CCNL1 and ZNF187 genes following adjustment for age, duration of diabetes, HBA1c and gender." (PMID 33178681, 2020).
head and neck cancer (2 papers, 2021 to 2025). A primary or metastatic malignant neoplasm affecting the head and neck. "CCNL1 encodes Cyclin L1 and its role as an oncogene in head and neck cancer by promoting cell cycle entry was previously proposed." (PMID 34298834, 2021). "Since CCNL1 amplification was previously associated with worse outcomes in head and neck cancer, we evaluated whether this could explain the differences we found in OPSCC." (PMID 34298834, 2021). "However, the role of CCNL1 as a candidate oncogene in head and neck cancer remains incompletely elucidated." (PMID 41106272, 2025).
metastatic prostate carcinoma (2 papers, 2020 to 2023). A carcinoma that arises from the prostate gland and has spread to other anatomic sites. "Further mechanism research revealed that NEAT1-1 could interact with cyclin L1 (CCNL1) through its #4 m6A and acted as a bridge between CCNL1 and cyclin dependent kinase 19 (CDK19) to form a stable complex, which may be specific in in bone metastatic prostate cancer." (PMID 37069649, 2023).
chronic hepatitis B (1 paper, 2026). "In addition, CCNL1 expression was elevated in chronic hepatitis B patients compared with those with resolved infection." (PMID 42198748, 2026).
diabetic retinopathy (1 paper, 2020). "Of particular interest, the CCNL1 gene was ranked 4th from a meta-analysis for association with severe diabetic retinopathy (P = 7.1 × 10–7), but was no longer top-ranked for association with diabetic retinopathy when individuals with nephropathy were removed from the case group." (PMID 33178681, 2020).
kidney stones (1 paper, 2020). "Based on published gene expression data from the Affymetrix® GeneChip® Whole Transcript Expression Arrays, CCNL1 was one of four genes differentially expressed in patients with kidney stones compared to controls (2.6 fold change, downregulated, P = 6.58E-05)." (PMID 33178681, 2020).
lymph node metastases (1 paper, 2005). "Finally, concerning lymph node metastases, CCNL1 and TP73L showed an increased frequency of gains (CCNL1: P=0.02; TP73L: P=0.05), while for SNO and PIK3CA no such correlation was observed." (PMID 15700036, 2005). "Performing multivariate logistic regression analysis, a significant association of CCNL1 gains and the presence of lymph node metastases was found, which was independent of anatomical site and T-stage of the primary tumour (P=0.049)." (PMID 15700036, 2005).
melanoma (1 paper, 2019). A malignant, usually aggressive tumor composed of atypical, neoplastic melanocytes. "Gene mutation is not a major component of CDK11A, CDK11B, CCNL1 or CCNL2 function in melanoma." (PMID 30987032, 2019). "We present data on CDK11, CCNL1 and CCNL2 mRNA expression in melanoma patients, including prognosis for survival." (PMID 30987032, 2019). "To understand CDK11 function in melanoma, we evaluated protein and RNA levels of CDK11, Cyclin L1 and Cyclin L2 in benign melanocytes and BRAF- as well as NRAS-mutant melanoma cell lines." (PMID 30987032, 2019).
oral carcinomas (1 paper, 2005). "Site-specific subgroup analysis further showed that copy number gains of CCNL1 and SNO occurred more frequently in oral carcinomas in advanced clinical stages as compared to N0 oral lesions (CCNL1: P=0.03; SNO: P=0.03)." (PMID 15700036, 2005).
ovarian carcinoma (1 paper, 2021). A malignant neoplasm originating from the surface ovarian epithelium. "Recently, CCNL1 promoter differential methylation was associated with platinum resistance in ovarian cancer, but its impact on gene expression was not evaluated." (PMID 34298834, 2021).
pancreatic cancer (1 paper, 2022). "We demonstrated that DCK and CCNL1 contribute to gemcitabine resistance in pancreatic cancer by performing genome-wide CRISPR/Cas9 knockout screening in the mouse pancreatic cancer cell line TB32047 under gemcitabine treatment." (PMID 35804923, 2022). "The knockout of DCK or CCNL1 by the CRISPR/Cas9 system promotes gemcitabine resistance in pancreatic cancer cells." (PMID 35804923, 2022). "In this study, we applied genome-wide CRISPR/Cas9 loss-of-function screening with gemcitabine treatment to identify DCK and CCNL1 as genes that contribute to gemcitabine resistance in pancreatic cancer and explored the mechanism of CCNL1-related gemcitabine resistance." (PMID 35804923, 2022). "We performed genome-wide CRISPR/Cas9 knockout screening in the mouse pancreatic cancer cell line TB32047 with gemcitabine treatment and identified deoxycytidine kinase (DCK) and cyclin L1 (CCNL1) as the top hits." (PMID 35804923, 2022). "Few studies have considered the role of CCNL1 in pancreatic cancer, and none have examined the connection between CCNL1 and gemcitabine resistance." (PMID 35804923, 2022).
polycystic ovary syndrome (1 paper, 2022). A disorder that manifests as multiple cysts on the ovaries. "The lnc-CCNL1-3:1 lncRNA is upregulated in polycystic ovary syndrome (PCOS) patients." (PMID 37533667, 2022).
tongue cancer (1 paper, 2023). A malignant neoplasm affecting the tongue. "Our findings revealed a significant elevation in the presence of Macro_apoec3a macrophages, contrasted by a considerable decrease in the infiltration levels of Macro_spp1, Macro_thbs1, and Macro_ccnl1 macrophages in tissues high in DDX5, when compared with tongue cancer specimens low in DDX5." (PMID 38136426, 2023).
type 1 diabetes (1 paper, 2020). "Both CCNL1 and ZNF187 were more highly expressed in renal glomeruli than other renal tissues, which may be consistent with DKD in people with type 1 diabetes primarily affecting the glomerulus." (PMID 33178681, 2020).
ZIKV infection (1 paper, 2024). "However, from the RNA-seq analysis, the ΔPSI of exon 6 of Cyclin L1 (CCNL1) was −0.123 and −0.11 in early and late acute samples respectively, and −0.847 in A549 ZIKV-infected cells, indicating that exon 6 was likely spliced out during ZIKV infection." (PMID 39065267, 2024).
cancer (12 papers, 2005 to 2025). A tumor composed of atypical neoplastic, often pleomorphic cells that invade other tissues. "Expression of both CDK11 and cyclin L1 is increased in various cancers, with amplification of CCNL1 associated with poor prognosis." (PMID 25837326, 2015). "Overexpression (usually associated with hypomethylation) of CCNL1 has been associated with cancer." (PMID 33178681, 2020). "Overexpression of CDK11 and/or Cyclin L1 in non-cancer silkworm cells resulted in an increased population of G1 phase cells and a corresponding decreased G2/M phase population." (PMID 30987032, 2019). "With regard to the clinical stage, the prevalence was significantly higher in stage IV carcinomas as compared to stage I–III carcinomas (CCNL1: P<0.001; SNO: P=0.05; PIK3CA: P=0.009; TP73L: P=0.03)." (PMID 15700036, 2005). "Both overexpression and inhibited expression of CDK11 and/or Cyclin L1 reduced the viability of these cells, suggesting a window of appropriate CDK11 levels in these non-cancer cells." (PMID 30987032, 2019).
tumor (10 papers, 2005 to 2025). "Taken together, the present study established a functional link between ES, miR-199b-5p and CCNL1, and suggested that miR-199b-5p acts as a tumor suppressor and may be of diagnostic and therapeutic importance for human ES." (PMID 26043836, 2015). "We found that GC patients with high DNA binding activities of SMARCA5 and E2F3 and high phosphorylation of CCNL1 (at T67) and SMC4 (at S41) in tumor tissues associated with poor prognoses (Log-rank test, p < 0.05)." (PMID 36788224, 2023). "In conclusion, the present study has demonstrated that miR-199b-5p acted as a tumor suppressor by targeting CCNL1 in ES cell lines." (PMID 26043836, 2015). "The Cyclin L1 antibody we developed labels nuclear speckles in tumour cells compatible with a role for CCNL1 in RNA splicing." (PMID 16598186, 2006). "In tumours, Cyclin L1 staining is mostly restricted to the nuclei of the epithelial cells with discrete additional cytoplasmic staining in some cells." (PMID 16598186, 2006). "In this large series of HNSCCs, we observed a high prevalence of CCNL1 gene overexpression, occurring in more than half of the tumours." (PMID 16598186, 2006). "Real-time quantitative PCR analysis of 96 HNSCCs and 82 of their counterpart normal tissues showed that Cyclin L1 gene expression levels were significantly different between tumours and normal tissue samples (T-test; P<0.0001)." (PMID 16598186, 2006). "In OSCC (n=85), CCNL1 and SNO copy number gains were primarily detected in tumours exhibiting lymph node metastases (CCNL1: P=0.03; SNO: P=0.03)." (PMID 15700036, 2005). "A total of 280 HNSCC tumours from 280 patients were analysed by FISH for copy number changes of proto-oncogenes CCNL1, SNO PIK3CA and TP73L located on chromosomal band 3q25–q29." (PMID 15700036, 2005). "Compared with other oncogenes, CCNL1 has its particularity and is quite active in the occurrence of many tumors, which may be a key node in the occurrence of tumor drug resistance." (PMID 39024509, 2024). "CCNL1 is not only a cell cycle regulatory protein, but also a potential oncogene, which can regulate tumor cell proliferation, invasion, drug resistance and other tumor-related biological behaviors." (PMID 39024509, 2024). "Altogether, these findings suggest that cyclin L1 might have a role in the RNA processing complex and could participate to tumour progression of HNSCC." (PMID 16598186, 2006). "The molecular mechanisms which promote tumour progression by CCNL1 remain to be determined." (PMID 15700036, 2005). "The corresponding chromosomal region harbors several potential proto-oncogenes, as for example, TP73L, PIK3CA, SNO and CCNL1, which may contribute to a more aggressive tumour progression." (PMID 15700036, 2005). "Additionally, miR-199b-5p may act as a tumor suppressor by repressing the expression of CCNL1 in ES cells." (PMID 26043836, 2015). "In order to validate the effect of CCNL1 on the progression and ADM-resistant of OS cells, we explored the expression levels of tumor-related genes MRP1, Survivin, and MMP2 in CCNL1-overexpressing HOS and 143B cells." (PMID 39024509, 2024). "Cell cycle proteins were evaluated based on their altered expression patterns (WAPAL, AHCTF1, etc.), phosphorylation patterns (CCNL1 T67, SMC4 S41, etc.), and inferred TF activities (SMARCA5, E2F3, etc.)in GC tumor tissues." (PMID 36788224, 2023). "Cyclin L1 (CCNL1) is a non-canonical cyclin that plays an important role in the regulation of tumor cell proliferation and lymph node metastasis." (PMID 39024509, 2024). "CCNL1, SOCS3, and HSPA6, which are highly expressed in patients with ccRCC, may promote tumor generation." (PMID 37293297, 2023). "The vast majority of genes were equally expressed in tumor and non-tumoral, control pituitary glands, including CCNL1, CCNE2, CCNB2, CCNA1, CDK18, CDK19 and CDK20." (PMID 35260162, 2022).
tumor (continued). "CCNL1 gene amplification, evaluated in 35 HNSCCs, was observed in 26% of the tumours and does not exceed three-fold (relative to the mean of 14 normal tissue samples)." (PMID 16598186, 2006). "Our results indicate that CCNL1 plays a critical role in the loco-regional progression of HNSCC and may serve as an indicator for occult advanced tumour stages." (PMID 15700036, 2005). "However, CCNL1 overexpression was also detected in 34% (nine out of 26) of tumours without CCNL1 gene amplification, showing that other transcriptionnal regulation factors are involved." (PMID 16598186, 2006).
infection (3 papers, 2025 to 2026). The state of being infected such as from the introduction of a foreign agent such as serum, vaccine, antigenic substance or organism. "The TAF1D isoform expressed during infection includes multiple exons downstream of the stop codon, and CCNL1 incorporates an additional exon with a PTC, so both transcripts are predicted NMD substrates." (PMID 39869630, 2025).
head and neck tumours (1 paper, 2006). "Interestingly, cyclin L1 was also observed in the nuclei of malignant cells of head and neck tumours, by histological immunodetection using our antibody." (PMID 16598186, 2006).
kidney disease (1 paper, 2020). "RNA-based gene expression data also supports a functional influence of CCNL1 and ZNF187 in kidney disease." (PMID 33178681, 2020). "Significant further research is required in populations that have blood derived, kidney biopsy derived and in vitro models with SNP, CpG, and gene expression data available for the same individuals to tease out the molecular signatures of these genes (CCNL1 and ZNF187) for kidney disease." (PMID 33178681, 2020). "Further supporting evidence for differential gene expression in CCNL1 and ZNF187 is presented from kidney biopsy and blood-derived RNA in people with and without kidney disease from NephroSeq." (PMID 33178681, 2020).
retinopathy (1 paper, 2020). "Subsequent studies have highlighted CCNL1 SNPs associated with retinopathy and measures of renal function." (PMID 33178681, 2020).
CCNL1 also shares sentences with these, for which no sentence is quoted: bone cancer (1 paper); endometrial cancer (1); Esophageal Neoplasms (1); Ewing sarcoma (1); gastric cancer (1); hepatitis B virus infection (1); kidney transplant (1); metabolic syndrome (1); Nephropathy (1); non-small cell lung carcinoma (1); osteosarcoma (1); Spastic paraplegia 7 (1); viral infection (1).